CCN5 (cellular communication network factor 5)
Description:
May play an important role in modulating bone turnover. Promotes the adhesion of osteoblast cells and inhibits the binding of fibrinogen to integrin receptors. In addition, inhibits osteocalcin production.
Synonyms: CTGF-L; WISP-2; CT58; WISP2
Tractability: Antibody: UniProt places it where antibodies can reach, with high confidence; UniProt predicts a signal peptide or a membrane-spanning region; its Gene Ontology location is reachable by antibodies, with medium confidence; the Human Protein Atlas places it where antibodies can reach.
Gene: Protein-coding gene on chromosome 20 (44,714,270 to 44,728,509, forward strand). Ensembl gene ENSG00000064205.
Subcellular location: Secreted
Subcellular location (Human Protein Atlas): Plasma membrane; Predicted to be secreted
Gene Ontology:
Molecular function: protein binding; heparin binding; integrin binding
Biological process: cell adhesion; cell-cell signaling; positive regulation of cell differentiation; signal transduction
Cellular component: extracellular region; non-collagenous component of interstitial matrix; nucleus; extracellular matrix
Genetic constraint (gnomAD): Loss-of-function variants: 17 observed, 17.32 expected, observed/expected ratio (o/e) 0.98, 90% interval 0.67 to 1.47. The upper end of that interval is the gene's LOEUF score, 1.47, which puts it in group 6 of 6, group 1 being the genes least tolerant of losing a copy. Missense variants: 367 observed, 325.84 expected, observed/expected ratio (o/e) 1.13, 90% interval 1.03 to 1.23. Synonymous variants: 135 observed, 135.83 expected, observed/expected ratio (o/e) 0.99, 90% interval 0.86 to 1.15.
Homologues: Orthologues: chimpanzee CCN5 (99% identical), macaque CCN5 (96% identical), dog CCN5 (85% identical), pig CCN5 (83% identical), guinea pig CCN5 (77% identical), mouse Ccn5 (73% identical), rat Ccn5 (69% identical), tropical clawed frog ccn5 (46% identical), zebrafish ccn5 (46% identical). Paralogues in human: CCN2 (45% identical), CCN3 (44% identical), CCN1 (40% identical), CCN4 (38% identical), CCN6 (32% identical).
Diseases named in the same sentence as CCN5 in open-access papers:
CCN5 is named in the same sentence as 107 diseases in open-access papers, as found by Europe PMC text mining. Sharing a sentence is not in itself a finding about the gene and the disease. The quoted sentences say what the papers report.
breast carcinoma (36 papers, 2009 to 2025). "Among the proteins implicated in these processes, CCN5 and E-cadherin have noticeably attracted oncologists’ attention in breast cancer research." (PMID 39144722, 2024). "However, we still know little about the mechanism underlying the correlations between CCN5 and E-cadherin expressions in breast cancer." (PMID 39144722, 2024). "Loss of CCN5 promoted EMT of the breast cancer cells through up-regulation of the TGF-βRII level." (PMID 30571728, 2018). "Studies have shown that the expression of CCN5 is inversely correlated with the aggressiveness of breast cancer, indicating its oncogenic/anti-invasive activity." (PMID 40016720, 2025). "Immunohistochemical staining using the SP method was performed to detect CCN5 and E-cadherin expression levels in 28 normal breast tissue samples, 52 primary breast cancer lesions, and paired recurrent chest wall lesions." (PMID 39144722, 2024). "Overall, the findings contribute to the growing body of evidence on the roles of CCN5 and E-cadherin in breast cancer progression and provide valuable insights for future research and clinical practice." (PMID 39144722, 2024). "Acknowledging these inconsistencies, the present study provided further evidence supporting the potential prognostic value of CCN5 and E-cadherin in breast cancer." (PMID 39144722, 2024). "This study aimed to analyze the expression levels and clinical significance of CCN5 and E-cadherin in primary and recurrent breast cancer lesions." (PMID 39144722, 2024). "Primary breast cancer lesions exhibited higher CCN5 and E-cadherin expression levels compared with recurrent lesions and normal tissues, although these differences were not statistically significant." (PMID 39144722, 2024). "CCN5 and E-cadherin were expressed at lower levels in recurrent breast cancer tissues and those with lymph node metastases, indicating their potential roles in breast cancer recurrence and metastasis." (PMID 39144722, 2024). "CCN5 is an important tumor suppressor gene that prevents the occurrence and development of breast cancer by inhibiting EMT." (PMID 39144722, 2024). "We can infer that CCN5 and E-cadherin work synergistically in the recurrence and metastasis of breast cancer, though the specific mechanism remains to be further revealed." (PMID 39144722, 2024). "In conclusion, the expression levels of CCN5 and E-cadherin in primary and recurrent breast cancer lesions, as well as in normal breast tissues were assessed, revealing their potential roles in breast cancer progression and metastasis." (PMID 39144722, 2024). "CCN5 and E-cadherin expression levels significantly differed among normal breast tissues, primary breast cancer lesions, and recurrent lesions (Χ2 = 18.934 and Χ2 = 14.516, p < 0.05)." (PMID 39144722, 2024). "A positive correlation between CCN5 and E-cadherin expression levels was found in breast cancer tissues (r = 0.398, p < 0.001)." (PMID 39144722, 2024). "We found that the CCN5 expression in primary breast cancer was higher than that in recurrent breast cancer and normal breast tissues." (PMID 39144722, 2024). "The glucocorticoid response to CCN5 in MDA-MB-231 breast cancer cells was mapped to a glucocorticoid response element (GRE) in the promoter region of CCN5." (PMID 34854055, 2022). "CCN5 has been previously reported to be transcriptionally induced by oestrogens and glucocorticoids in breast cancer cells." (PMID 34854055, 2022). "In noninvasive breast cancer cell lines, several genetic exposures disrupt CCN5, which is responsible for invasive cancer phenotypes." (PMID 34940056, 2021). "Over the last decade, several studies, including our laboratory, have revealed the modulatory roles of CCN5 in breast cancer progression." (PMID 33745223, 2021). "Collectively, these studies indicate that leptin-induced ER-α-positive breast cancer cell viability is mediated via suppressing CCN5 expression." (PMID 29370782, 2018).
breast carcinoma (continued). "It was also shown that CCN5 is strongly expressed in non-invasive breast cancer cells in which it down-regulates the expression of TGF-β receptor II (TGF-βRII) at the transcriptional level." (PMID 30571728, 2018). "The role of CCN5 in human pathology is mainly attributed to its function in proliferation and mobilization of breast cancer and pancreatic adenocarcinoma cells and proliferation of vascular smooth muscle cells." (PMID 30571728, 2018). "CCN5/WISP2 is regulated by hypoxia through the HIFα isoforms in low-invasive luminal-like breast cancer cell lines, preferentially by HIF2α." (PMID 29247377, 2018). "Taken together, these results indicate that leptin suppresses CCN5 expression in ER-α-positive breast cancer cells at the transcription level." (PMID 29370782, 2018). "WISP2 or CCN5 is a transcriptional repressor that acts as a negative regulator of breast cancer progression." (PMID 30404206, 2018). "WISP4 knockdown by sh-CCN5 in MCF-7 breast cancer cells leads to an increased expression of the components of the TGFB1 (TGF-β) signaling pathway and induction of breast cancer invasiveness." (PMID 26395334, 2015). "Another implication was that CCN5 inhibited EMT to reduce the migration of breast cancer cells." (PMID 39144722, 2024). "Given the complex interaction among CCN5, E-cadherin, and breast cancer progression, the present study aimed to elucidate their expression levels and clinical significance in primary and recurrent breast cancer lesions." (PMID 39144722, 2024). "Importantly, a positive correlation was identified between CCN5 and E-cadherin expression levels in primary breast cancer tissues, indicating a potential synergistic effect in breast cancer recurrence and lymph node metastases." (PMID 39144722, 2024). "While statistically significant, the weak strength of the correlation suggests that other factors may influence the expression patterns of CCN5 and E-cadherin in breast cancer progression." (PMID 39144722, 2024). "Both CCN5 and E-cadherin negatively regulated breast cancer via the EMT mechanism." (PMID 39144722, 2024). "Correlation between CCN5 and E-cadherin expression levels in primary breast cancer." (PMID 39144722, 2024). "In addition to the findings of the present study, it is important to consider existing literature on the prognostic significance of CCN5 and E-cadherin in breast cancer." (PMID 39144722, 2024). "The findings of the present study suggested that CCN5 and E-cadherin expression levels could serve as valuable biomarkers in breast cancer, with potential benefits for clinical practice." (PMID 39144722, 2024). "Although EGCG upregulates CCN5 expression in breast cancer cells, the link between CCN5 activation and EGCG‐mediated suppression of TNBC cell viability is unknown." (PMID 33745223, 2021). "Thus, inducing CCN5 activity in breast cancer tissues can be a promising therapy against breast cancer." (PMID 34940056, 2021). "The pro-tumorigenic CCN1, CCN2, CCN3, and CCN4 may lead to human breast cancer, although the anti-tumorigenic actions of CCN5 and CCN6 are also present." (PMID 34940056, 2021). "However, in case of more invasive breast cancer such as ER-negative breast cancer, CCN5 expression is minute." (PMID 34940056, 2021). "In addition to suppressing breast cancer cell viability, reprograming of MET, a hallmark of reversing cancer stemness mechanism, is also known to be regulated by CCN5 through TGF‐β‐mediated signaling." (PMID 33745223, 2021). "CCN5 acts as a tumor suppressor in the breast cancer cell lines." (PMID 34940056, 2021). "In breast cancers, CCN5 is only detected in non‐invasive cells." (PMID 33745223, 2021). "We next determined whether suppression of CCN5 by leptin is a relevant episode in leptin-mediated ER-α-positive breast cancer cell viability." (PMID 29370782, 2018).
breast carcinoma (continued). "Notably, CCN5 enhances MET of pancreatic cancer cells and loss of CCN5 promotes EMT and acquisition of stem cell-like phenotypes in estrogen-dependent MCF7 breast cancer cells." (PMID 30571728, 2018). "CCN5/WISP2 is also negatively correlated with tumor macrophage invasion in breast cancer samples which could provide an additional marker for a better tumor prognosis." (PMID 29247377, 2018). "CCN5/WISP-2 is an anti-invasive molecule and prevents breast cancer (BC)progression." (PMID 28530705, 2017). "However, CCN5 has been poorly studied on ER positive advanced breast cancer." (PMID 40016720, 2025). "The aim of this study was to investigate the expression and clinical implications of CCN family member 5 (CCN5) and the oestrogen receptor (ER) in advanced breast cancer (BC)." (PMID 40016720, 2025). "However, Smad6 can prevent the phosphorylation of other Smad members and therefore act as a negative regulator of the TGFβ mediated pathway and previous studies have shown that silencing CCN5/WISP2 expression in the breast cancer cell line MCF-7 decreases Smad6 expression levels." (PMID 29247377, 2018). "CCN5 and E-cadherin are proteins involved in cell adhesion and epithelial-mesenchymal transition (EMT), playing roles in breast cancer progression." (PMID 39144722, 2024). "While the expression of CCN proteins varies in different cancer types, CCN1, CCN2, CCN3 and CCN4 participate in tumor development and act as oncogenes, but CCN1, CCN3, CCN5, and CCN6 inhibit tumor growth and play tumor-suppressive roles in breast carcinomas." (PMID 34940056, 2021). "These recent advances, exploring the role of CCN5‐signaling in breast cancer, strongly suggest that targeting TNBC‐BCSC by activating CCN5 would be an ideal strategy to prevent breast tumors’ growth and relapse." (PMID 33745223, 2021). "Cellular communication network factor 5 (CCN5) inhibits the stemness, reverses the EMT process in breast cancer cells, and activates ER-α in TNBC cells." (PMID 34948368, 2021). "Expression of CCN5 is highly upregulated by estrogen, especially in MCF-7 breast cancer lines that express estrogen receptor alpha (ESR1), making it an oncogene." (PMID 26395334, 2015). "CCN5 and E-cadherin expression levels in breast cancer patients with and without lymph node metastases." (PMID 39144722, 2024). "CCN1, CCN3, CCN5 and CCN6 may play dual roles; their expression can inhibit breast cancer growth, and their absence can induce carcinoma." (PMID 34940056, 2021). "CCN1, CCN2, CCN3, and CCN4 are pro-tumorigenic and may be responsible for human breast carcinoma; while CCN1, CCN3, CCN5 and CCN6 have anti-tumorigenic effects." (PMID 34940056, 2021). "CCN1, CCN3, CCN5, CCN6 play a critical role in survival in breast cancer." (PMID 34940056, 2021). "CCN5/WISP2 has also been reported to be directly regulated by estrogen in the human breast cancer cell line MCF-7 and non-transformed human mammary epithelial cells, and is more highly expressed in a less-aggressive breast cancer cell line (MCF-7) compared with a highly aggressive (MDA-MB-231)." (PMID 29247377, 2018). "Finally, the mechanism of how CCN5 regulates ER-positive advanced breast cancer is not clear." (PMID 40016720, 2025). "CCN5 is the only protein in the CCN protein family where the CT module containing carboxyl domain is absent and it plays an anti-tumorigenic effect on breast cancer." (PMID 34940056, 2021). "However, it is well documented that CCN5 may inhibit phosphorylation of AKT in both estrogen-receptor α (ER-α)–negative and ER-α–positive breast cancer cells as well as in certain other cancer cell lines." (PMID 36529291, 2023). "The promoter region of the CCN5 gene has previously been reported to contain a putative glucocorticoid response (enhancer) element (GRE) (5′-GGTACGTACTGTTCC-3′) and to respond to glucocorticoid stimulation (dexamethasone) in estrogen receptor alpha (ERα)-negative MDA-MB-231 breast cancer cells." (PMID 34854055, 2022).
cardiac hypertrophy (11 papers, 2015 to 2025). "Similarities of these domains has been illustrated by removing the CK domain from CCN2 causing CCN2 to act similar to CCN5, i.e. to inhibit myocardial hypertrophy following aortic constriction in mice." (PMID 37245184, 2023). "Under normal chow diet, CCN5 knockout caused mild obesity, adipocyte hypertrophy, mild hyperglycemia, mild hyperinsulinemia, cardiac hypertrophy, lipid accumulation, fibrosis, and cardiac deficiency, and decreased water intake." (PMID 34948212, 2021). "Likewise, appending the CK domain of CCN2 onto CCN5 caused enhanced myocardial hypertrophy, similar to that elicited by CCN2." (PMID 37245184, 2023). "Previously, the differential expression and opposing effects of CCN2 and CCN5 on the development of cardiac hypertrophy and fibrosis has been reported." (PMID 34948212, 2021). "Collectively, these data indicate that CCN5 KO mice exhibit arrays of lipotoxic cardiomyopathy phenotypes including cardiac hypertrophy, ectopic lipid accumulation, fibrosis, and cardiac dysfunction." (PMID 30485307, 2018). "CCN5/WISP2 was shown to protect from cardiac hypertrophy and fibrosis in response to pressure overload when compared to a CTGF-overexpressing model." (PMID 29247377, 2018). "Cardiac hypertrophy, ectopic lipid accumulation, and impaired lipid metabolism in hearts were observed in the CCN5 KO mice, as determined using histology, quantitative RT-PCR, and western blotting." (PMID 30485307, 2018). "H&E staining of heart sections and measurements of CSA revealed that CCN5 KO led to cardiac hypertrophy." (PMID 30485307, 2018). "Interestingly, transgenic mice expressing CCN5/WISP-2 were protected against cardiac hypertrophy and fibrosis due to overload pressure, with reduced Smad2/3 and Smad4 levels." (PMID 34063397, 2021). "CCN5 exerted an opposing function in CCN2-induced cardiac hypertrophy and fibrosis." (PMID 25901787, 2015). "CCN2 and CCN5 were found to be upregulated during the development of cardiac hypertrophy." (PMID 25901787, 2015). "However, CCN2 expression accelerates cardiac fibrosis and hypertrophy, whereas CCN5 exerted anti-hypertrophic and -fibrotic effects, indicating that CCN5 antagonizes CCN2 function during the development of cardiac hypertrophy and fibrosis." (PMID 25901787, 2015).
pancreatic cancer (11 papers, 2010 to 2021). "In most TNBC cells and pancreatic cancer cells, which are aggressive in nature and mesenchymal type, CCN5 expression is undetected." (PMID 33745223, 2021). "For example, pancreatic cancer cells undergo a MET when exposed to recombinant WISP-2/CCN5, suggesting that the protein is required for maintaining an epithelial state." (PMID 24281218, 2010). "We found that EGCG has the potency to upregulate CCN5 in TNBC and pancreatic cancer cells in a dose‐dependent manner and at the transcription level." (PMID 33745223, 2021). "CCN5, previously known as WISP-2, rCop-1, COP-1, HICP and CTGF-L, can perform a regulatory role by reducing epithelial-to-mesenchymal transition (EMT) in both breast and pancreatic cancer cells." (PMID 34940056, 2021). "Interestingly, WISP-2/CCN5, a member of the WNT1-inducible signaling pathway (WISP), is down-regulated in pancreatic adenocarcinoma and in cell lines from pancreatic carcinoma." (PMID 24281218, 2010).
breast tumor (10 papers, 2009 to 2025). "In a very recent study, the immunomodulatory properties of CCN5 have been reported, according to which CCN5 can enhance the susceptibility of breast tumors to cytotoxic T‐lymphocyte (CTL)‐mediated lysis." (PMID 33745223, 2021). "As the breast tumour progresses, the expression level of CCN5 decreases gradually, suggesting it has a role in inhibiting the transition of breast tumour epithelium from non-invasive to invasive stages." (PMID 40016720, 2025). "Consistent with in vivo results, further studies have shown that CCN5 is differentially expressed in various breast tumor cell lines and its expression profile is varied depending on the microenvironment and the aggressive nature of the cells." (PMID 29370782, 2018). "In summary, our studies illustrate how a single signaling pathway (CCN5-signaling) can control breast tumor growth and progression via regulating sequential, multistep molecular signatures that are linked with apoptosis, EMT program and stemness." (PMID 28450698, 2017). "Thus, it is needed to differentiate whether the cells deficient of CCN5-signaling assumes TIC-like behavior and forms aggressive breast tumors in xenograft model." (PMID 28450698, 2017).